EGFR (epidermal growth factor receptor)
Diseases named in the same sentence as EGFR in open-access papers (continued):
Sharing a sentence is not in itself a finding about the gene and the disease.
gastric cancer (continued). "Similarly, macrophages induced gastric cancer cell EGFR, AKT tyrosine phosphorylation, and therefore stimulated cancer cell motility and migration." (PMID 35237300, 2022). "The epidermal growth factor receptor (EGFR), another tyrosine kinase receptor, is involved in the regulation of gastric mucosa proliferation and progression of gastric carcinomas through the Ras/MEK-ERK signaling pathway, and its overexpression is associated with poor prognosis in gastric cancer." (PMID 35646067, 2022). "Notably, LPA stimulated EGFR transactivation via an MMPs-dependent mechanism in gastric cancer, which was partly responsible for enhancing geminin stability in the S phase and promoting DNA replication." (PMID 34658851, 2021). "Thus, LPA promotes S-phase cell-cycle progression in gastric cancer cells via the LPAR3/MMPs/EGFR/PI3K/mTOR signaling axis." (PMID 34658851, 2021). "Thus, LPA enhances geminin stability via the LPAR3/MMPs/EGFR/PI3K/mTOR signaling axis in gastric cancer." (PMID 34658851, 2021). "In gastric cancer, similar to prostate cancer, EGFR was of a higher level in exosomes, and recently, tripartite motif-containing 3 (TRIM3) was found to be decreased in the serum of gastric cancer patients, making exosomal TRIM3 a potential biomarker of gastric cancer." (PMID 33922480, 2021). "Given our observation, LPA stabilized geminin via the LPAR3/MMPs/EGFR/PI3K/mTOR signaling axis in gastric cancer cells, we examined whether this pathway modulated cell-cycle progression." (PMID 34658851, 2021). "Moreover, these antibody combinations bypass the resistance to treatment induced by monotherapy with cetuximab (anti-EGFR mAb) in colorectal cancer and with an anti-cMET antibody in gastric cancer." (PMID 34572847, 2021). "In addition, ECM1-mediated integrin β4 promotes EMT and glucose metabolism via SOX2/HIF-1α signaling in gastric cancer and modulates epidermal growth factor receptor (EGFR) signaling to induce gefitinib chemoresistance." (PMID 33406733, 2021). "We investigated whether MMPs or EGFR inhibition influences LPA-induced efficient cell proliferation in gastric cancer cells with the CCK-8 assay." (PMID 34658851, 2021). "To determine whether LPA is involved in EGFR transactivation in gastric cancer, we first examined the changes in EGFR phosphotyrosine level upon LPA (10 μM) stimulation." (PMID 34658851, 2021). "Indeed, the acceleration of cell cycle on the addition of cetuximab selectively in epirubicin-treated EGFR-amplified gastric cancer PDOs was further confirmed using a thymidine analog-based DNA incorporation FACS assay." (PMID 33199443, 2021). "Notably, in the case of gastric cancer, EGFR can be delivered in tumor-derived exosomes into the liver where it fuses with the plasma membranes of liver stromal cells, preparing the metastatic niche." (PMID 34684727, 2021). "Whether CD148 dephosphorylates ERK1/2 directly or through EGFR-deactivation in gastric cancer cells will be clarified in future work." (PMID 32201537, 2020). "MiR-138 can influence the progression of gastric cancer by regulating EGFR." (PMID 33390953, 2020). "Adamalysines might be involved in the pathogenesis of gastric cancer and involved in EGFR signaling pathway and TGF-β/Smad pathway." (PMID 32610677, 2020). "Notably, KISS1, TIMP2, MMP11, IGFBP1, and EGFR have been reported to be involved in the metastasis of gastric cancer." (PMID 32117443, 2020). "Ongoing clinical trials of EGFR inhibitors continue to play a critical role in the evaluation of efficacy, safety profile, and overall response and survival rates in patients with advanced gastric cancer." (PMID 32850413, 2020).
gastric cancer (continued). "Tan IIA also inhibited the growth of gastric cancer AGS cells via suppressing epidermal growth factor receptor (EGFR), insulin like growth factor receptor (IGFR), vascular endothelial growth factor receptor (VEGFR) expression and blocking PI3K/Akt/mTOR, Ras/Raf/MEK/ERK pathways." (PMID 32776119, 2020). "In another study, levels of EGF, EGFR and a homolog of EGFR (c-erb-B2) were shown to be elevated in gastric mucosa of patients suffering from chronic gastritis with a Helicobacter pylori infection, and were comparable to samples from gastric cancer patients." (PMID 32302357, 2020). "The most recognized in gastric cancer overexpression are EGFR and HER2." (PMID 32850413, 2020). "The epidermal growth factor receptor (EGFR) is overexpressed in gastric cancers." (PMID 32963532, 2020). "Treatment of the control shRNA cell line with EGF induced a marked increase in cell migration, suggesting that EGF receptor (EGFR) signaling might be involved in gastric cancer metastasis." (PMID 30976198, 2019). "This study aims to investigate whether lycopene inhibits proliferation and induces apoptosis in gastric cancer AGS cells by suppressing the EGFR/Ras/MAPK and NF-κB-COX-2 signaling axis." (PMID 31491956, 2019). "EGFR inhibitors could be potential agents to eradicate cytotoxic anticancer drug-tolerant gastric cancer cell populations." (PMID 31607750, 2019). "EGFR expression was found to be related to survival in gastric cancer patients." (PMID 31318186, 2019). "We tested whether MICAL‐L2 plays a role in the EGFR expression in gastric cancer cells and determined the specific mechanisms involved." (PMID 31034158, 2019). "When we analysed the role of Cdc42 on EGFR stability in gastric cancer cells, we observed that the silencing of Cdc42 impaired MICAL‐L2‐induced EGFR up‐regulation and active form of Cdc42 significantly rescued the attenuated EGFR expression in MICAL‐L2‐depletion cells." (PMID 31034158, 2019). "The positive EGFR expression rate was 14.5% in gastric cancer tissue." (PMID 31318186, 2019). "Sulforaphene could also promote human gastric cancer cell apoptosis by downregulating EGFR and p-ERK1/2 and inhibiting the MAPK signaling pathway." (PMID 31889894, 2019). "We found that EGFR expression to be a predictive biomarker for cetuximab on gastric cancer." (PMID 31331301, 2019). "However, as indicated in this paragraph, the relevance of MET as resistance factor to EGFR-targeted therapies was already shown in various cell lines, including gastric cancer cell lines, and in clinical samples." (PMID 31557260, 2019). "EGFR has a wide range of expression in gastric cancer ranging from 2 to 44%." (PMID 30621788, 2019). "It was reported that sulforaphene could decreases human gastric cancer cell viability and induces apoptosis via EGFR, p-ERK1/2 down-regulation pathway." (PMID 31889894, 2019). "miR-370 also enhances cell proliferation and migration in gastric cancer by targeting EGFR." (PMID 31492116, 2019). "However, there are some reports about the positive role of EGFR expression in gastric cancer patients and improving the survival of such patients." (PMID 30621788, 2019). "However, the small sample size made the statistical power limited and larger sample size studies relevant to HER2/c-erbB-2, EGFR protein expression in gastric carcinoma and its clinical significance were needed to further discussion it correlation." (PMID 33817143, 2019). "It has been reported that miR-20a/LRIG1 axis might regulate gastric cancer drug resistance through EGFR-mediated PI3K/AKT and MAPK/ERK signaling." (PMID 30497428, 2018).
gastric cancer (continued). "Similarly, in vitro experiments, EGFR can induce proliferation and migration of gastric cancer cells, and silent expression of EGFR can significantly inhibit the proliferation and migration of gastric cancer cells." (PMID 30524285, 2018). "Therefore, in order to know the mechanism behind this, we tested interaction between EGFR and integrin β4 on the influence of proliferation and apoptosis of gastric cancer cell lines by blocking or promoting β4 synthesis with or without gefitinib." (PMID 29618949, 2018). "Interestingly, EGFR expression was increased in 68.42% (39/57) of NOX4-positive gastric cancer patients." (PMID 30237423, 2018). "Anyway, EGFR plays different roles in gastric cancers and lung adenocarcinomas." (PMID 30087428, 2018). "And gastric cancer patients benefit little from anti-EGFR MoAbs targeted therapy." (PMID 30416987, 2018). "This CD137 induction was dependent upon EGFR expression levels on gastric cancer cells (Spearman correlation test; p < 0.001), with NK cells promoting cetuximab-mediated cytotoxicity in the EGFR-expressing gastric cancer cell lines MKN-1 and MKN-45." (PMID 30321186, 2018). "Our preliminary findings suggested that CT texture analysis could have few potential applications in assessing the expression of EGFR in gastric cancer." (PMID 30087428, 2018). "To further explore the clinical correlation between NOX4 and EGFR expression in gastric cancer patients, we examined NOX4 expression in gastric cancer tissues and the paired adjacent normal tissues from 90 patients by IHC using anti-EGFR or anti-NOX4 antibodies." (PMID 30237423, 2018). "The present meta-analysis demonstrated that high EGFR expression significantly predicts poor prognosis, suggesting that high EGFR expression may serve as a predictive biomarker for poor prognosis in patients with gastric cancer." (PMID 28199988, 2017). "LINC00152 was overexpressed in tumor tissues and plasma of gastric cancer (GC) patients, and could promote GC cell proliferation and cell cycle progression through regulating EGFR and EZH24–7." (PMID 29180678, 2017). "In all, the current study indicated that acetylcholine could act through M3 muscarinic receptor to activate the EGFR signaling and promote gastric cancer cell proliferation." (PMID 28102288, 2017). "Together, these findings indicated that the autocrine ACh could act through M3R and the EGFR signaling to promote gastric cancer cells proliferation, targeting M3R or EGFR may provide us a potential therapeutic strategy for gastric cancer treatment." (PMID 28102288, 2017). "So we then investigated whether ACh could act through M3R to activate EGFR signaling in gastric cancer cells." (PMID 28102288, 2017). "The exact mechanism between M3R and EGFR is still unclear in gastric cancer." (PMID 28102288, 2017). "Cbl-b knockdown could promote cell proliferation and reduce apoptosis induced by 5-fluorouracil treatment in gastric cancer cells via the EGFR pathway." (PMID 28915662, 2017). "Here, we investigated the relationship between CD24 and EGFR in gastric cancer cells." (PMID 26830684, 2016). "In gastric cancer cells, Cbl-b could inhibit the survival signal of EGFR pathway to inhibit the proliferation induced by 5-FU treatment." (PMID 27494897, 2016). "Overall, the fact that CD24 interacted with EGFR and was crucial for activation of EGFR downstream effectors and cell migration, allowing us to conclude that regulation of EGFR stabilized expression can thus be a novel mechanism for CD24-induced gastric cancer progression." (PMID 26830684, 2016). "However, when we analyzed the role of RhoA protein on EGFR stability in gastric cancer cells, we observed that the inhibition of RhoA impaired EGFR expression and active RhoA markedly increased EGFR expression." (PMID 26830684, 2016). "Overall, the clinical data support our in vitro results that CD24 may play a role as an EGFR supporter to promote gastric cancer progression." (PMID 26830684, 2016).
gastric cancer (continued). "By reducing tyrosine kinase phosphorylation of homodimers or heterodimers of the two receptors, lapatinib blocks EGFR or HER2 signal transduction, thereby inhibiting cell growth of gastric cancers that overexpress EGFR or HER2 and enhancing cancer cell apoptosis." (PMID 26880889, 2016). "EGFR expression is correlated with poor clinical outcome in gastric cancer." (PMID 27738318, 2016). "In addition, we noticed that the effect of CD24 on EGFR stability was mediated by RhoA activity in SGC-7901 gastric cancer cells." (PMID 26830684, 2016). "Accordingly, upregulation of EGFR expression is central to gastric cancer cell metastatic behavior." (PMID 26830684, 2016). "The results obtained in this study clearly established a novel relationship between CD24 and EGF/EGFR signaling in the context of migration regulation, which could be essential in promoting aggressiveness of gastric cancer." (PMID 26830684, 2016). "We revealed that berberine inhibited EGFR signaling pathway in gastric cancer." (PMID 27738318, 2016). "In gastric cancer, asporin contributes to metastasis through EGFR and ERK-CD44/MMP-2 pathways." (PMID 27705916, 2016). "To be consistent with this, we found that there were positive correlations between the expression of EHF and HER receptors in a cohort of gastric cancers including EGFR, HER2 and HER3, particularly HER2, in a cohort of gastric cancers, as supported by the information from TGCA database." (PMID 27787520, 2016). "MKN45, BGC823 and SGC7901 were EGFR-positive gastric cancer cells." (PMID 27738318, 2016). "The EGF/EGFR pathway is involved in the progression of gastric cancer." (PMID 26795388, 2016). "Since pathological stage II/III gastric cancer is diagnosed after operation, postoperative adjuvant administration of anti-EGFR antibody in addition to the standard therapy may be a promising strategy for such gastric cancer." (PMID 25154973, 2015). "In this study, we explored NTR1, β-catenin and EGFR expression in gastric cancer." (PMID 26215716, 2015). "Our findings help to indicate the hypermethylation at EGFR promoter in gastric cancer and it could be a potential epigenetic biomarker for gastric cancer status and progression." (PMID 25959250, 2015). "In our study, we used the Sequenom EpiTYPER assay to study the relationship between the methylation changes of the EGFR promoter and gastric cancer as well as its clinical characteristics such as histology differentiation, histologic grading, infiltration, TNM stage, and distant metastasis." (PMID 25959250, 2015). "The hypermethylation at EGFR promoter in gastric cancer was first detected in our study." (PMID 25959250, 2015). "Given the rarity of high-level EGFR amplification in gastric cancers, a benefit of amplified patients from cetuximab could have potentially been missed." (PMID 25649416, 2015). "Thus, antisense inhibition of EGFR expression results in dramatic growth inhibition of gastric cancer cell lines with EGFR overexpression." (PMID 25154973, 2015). "EGFR expression in primary gastric cancer was examined using immunohistochemistry (IHC)." (PMID 25154973, 2015). "EGFR amplification may be of relevance to gastric cancer as a multitude of drugs exists that target EGFR." (PMID 25649416, 2015). "Intra-tumor heterogeneity is a potential cause for failure of targeted therapy in gastric cancer, but the extent of heterogeneity of established (HER2) or potential (EGFR, CCND1) target genes and prognostic gene alterations (MYC) had not been systematically studied." (PMID 25649416, 2015). "Approximately 30 % of gastric cancers are reported to show EGFR overexpression." (PMID 25185971, 2015). "According to the least squares method of analysis, when the ND score was above 35%, the risk that the EGFR expression score was IHC 2+ rather than IHC 1+ was 8.19 times higher for 13th JGCA pStage II/III gastric cancers treated with S-1 (P = 0.0053)." (PMID 25154973, 2015).
gastric cancer (continued). "In addition, preclinical data suggest that a subset of gastric cancers (20%) with EGFR amplification and overexpression can respond to cetuximab therapy." (PMID 25784931, 2015). "In summary, we found hypermethylation at the EGFR promoter in gastric cancer, which could be one of the mechanisms for high expression level of EGFR in gastric cancer." (PMID 25959250, 2015). "We found a significant increased level of EGFR and p-EGFR in gastric cancers." (PMID 26538117, 2015). "We aimed to investigate whether methylation status of the EGFR promoter correlates with malignancy and patient outcome in gastric cancer." (PMID 25959250, 2015). "In addition, high tumor EGFR and HER2 expression levels were associated with an unfavorable outcome in patients with resectable gastric cancer." (PMID 25788990, 2015). "The EGFR may be one of the most optimal molecular targets in therapy of aggressive gastric cancer, which is resistant to the current standard chemotherapy regimens." (PMID 25154973, 2015). "EGFR inhibition may, therefore, prove to be the optimal target for therapy of gastric cancer with high ND, when used as a postoperative adjuvant therapy." (PMID 25154973, 2015). "EGFR, which is a member of the same family of receptor tyrosine kinases, may similarly be a good prognostic marker in advanced gastric cancer." (PMID 24348859, 2014). "Decreased core-fucosylation in gastric cancer might be associated with lower core-fucosylation of EGFR, and thus with reduced activation of EGF-induced phosphorylation of the EGFR pathway." (PMID 24732908, 2014). "In particular, Nedd4-1 mediates EGF-dependent gastric cancer cell invasion and migration, suggesting that Nedd4-1 may participate in EGFR-mediated tumor metastasis signaling." (PMID 25395181, 2014). "ErbB4 mutations have been described to occur in lung, breast, gastric cancer and melanoma and like for ErbB3 differ from those observed in EGFR or HER2 by not displaying characteristic mutational hotspots." (PMID 24643470, 2014). "Although colorectal tumors with an activating mutation of the Kirsten(K)-ras gene are not sensitive to EGFR antibodies, the incidence of K-ras mutations in gastric cancer appears to be low." (PMID 24758484, 2014). "Crosstalk between EGFR and integrins facilitates gastric cancer cell invasion and proliferation." (PMID 25398317, 2014). "Although there are parallels, the Her2-gastric cancer algorithm differs from EGFR GCN in CRC." (PMID 24940619, 2014). "In the previous study, we found that rs2293347 in the gene of human epidermal growth factor receptor (EGFR) is a candidate SNP related to the chemotherapeutic response; we achieved this result by applying our combined method to gastric cancer patients who were treated with fluoropyrimidine." (PMID 25127363, 2014). "EGFR expression is a good prognostic marker for patients with gastric cancer." (PMID 24348859, 2014). "But miR-302b function as a tumor suppressor gene both in gastric cancer by targeting EGFR." (PMID 24438167, 2014). "The overexpression of EGFR in gastric cancer has been confirmed in a number of studies." (PMID 23833649, 2013). "The levels of phospho-ERK transiently decreased and then elevated by 48 h in MGC803 cells, which implied that the EGFR/ERK/Akt signaling pathway may be involved in 5-FU activity in gastric cancer cells." (PMID 24351824, 2013). "The results of the present investigation demonstrated that the EGFR/CD3 BsAb significantly enhanced the cytotoxic activity of CIK cells to gastric cancer cells in vitro and in vivo, so this BsAb may potentially aid cellular therapy." (PMID 23833649, 2013). "Additionally, it was demonstrated to predict clinical outcome in advanced gastric cancer during combination therapy with Folfiri and cetuximab but tumor metabolism has not been analyzed in terms of single agent treatment with an EGFR mAB." (PMID 22439666, 2012). "Agents targeting human EGFR remain very controversial in treating gastric cancer." (PMID 22709792, 2012).